INS (insulin)
Diseases named in the same sentence as INS in open-access papers (continued):
Sharing a sentence is not in itself a finding about the gene and the disease.
metabolic disorders (continued). "Due to the role of skeletal muscle glucose uptake as a critical determinant of insulin sensitivity and progression of metabolic diseases, hypoxia is also in the focus of diabetes research." (PMID 38339185, 2024). "Meta-analyses of randomized clinical trials demonstrated that berry supplementation reduces cardiovascular and metabolic disease risk markers (e.g., total cholesterol, triglycerides, LDL-cholesterol, fasting glucose, fasting insulin, triglycerides, and HbA1c)." (PMID 38337686, 2024). "This has prompted a growing number of reports investigating the role of IRS proteins in mediating insulin response, not only in the context of metabolic disorders but also in relation to cancer." (PMID 38272982, 2024). "Adiponectin is another adipokine that enhances insulin sensitivity, reduces inflammation, and increases fatty acid oxidation, but it is often downregulated in metabolic disorders." (PMID 39049964, 2024). "We included not only glucose and insulin as indicators of glucose metabolism but also insulin resistance indices so that the results would be more consistent with the effects of metabolic diseases." (PMID 38425754, 2024). "Based on the remarkable conservation in the players and responses to altered insulin signaling in metabolic health, we were curious if human WDR23 was associated with metabolic disease states." (PMID 38767782, 2024). "Inflammation, ectopic lipid deposition, endoplasmic reticulum stress (ERS), and oxidative stress are involved in the onset and progression of T2D and TOD by impairing insulin sensitivity and/or β cell dysfunction, reciprocal with metabolic disorders." (PMID 39353925, 2024). "DM is a common metabolic disorder resulting from abnormalities in insulin secretion, insulin function, or a combination of both." (PMID 39074834, 2024). "For example, in the context of metabolic diseases, emerging evidence suggests that ILC2s play a role in adipose tissue homeostasis and insulin sensitivity." (PMID 39416774, 2024). "Horses are monogastric mammals that develop similar clinical pathologies as humans regarding metabolic disorders and insulin signaling." (PMID 38886475, 2024). "It is a metabolic disorder characterised by inadequate insulin secretion and peripheral tissue resistance to insulin’s effect." (PMID 39458491, 2024). "This meta-analysis provides evidence supporting the beneficial effects of myricetin supplementation on metabolic parameters, particularly in improving glucose regulation, insulin sensitivity, and lipid profiles in mice models of metabolic disease." (PMID 39519561, 2024). "Dysfunction of mitochondria has adverse effects on glucose and lipid metabolism, oxidative capacity, insulin sensitivity, adipocyte differentiation, and thermogenesis in adipocytes, ultimately contributing to metabolic diseases." (PMID 38786764, 2024). "PCOS‐related regions are mostly connected to metabolic disorders, inflammation, the regulation of insulin signaling, and cancer." (PMID 38468402, 2024). "Hormonal signals such as catecholamines and insulin act on adipocyte LDs, and impaired responsiveness to these signals can lead to uncontrolled lipolysis, lipotoxicity, and metabolic disease." (PMID 38130664, 2023). "To date, several studies have demonstrated the insulin-sensitizing effect of inositols, specifically in their physiological 40:1 ratio, in various endocrine and metabolic disorders; however, to date, only one trial has evaluated the use of inositols in T2DM." (PMID 38137721, 2023). "In this line of research, intermittent fasting and time-restricted eating have been shown to improve glucose metabolism and insulin sensitivity in individuals with metabolic diseases." (PMID 37445852, 2023). "This disease presents a multiple etiology of metabolic disorder, which induces chronic hyperglycemia and disorders of carbohydrates, proteins, and fats metabolism, a direct result of losses in the secretion of insulin, the action of insulin, or both." (PMID 37144218, 2023).
metabolic disorders (continued). "Mapping the molecular pathways of insulin signaling, estrogen signaling, and their interplays advances our understanding of metabolism and discovery of new therapeutic options for metabolic disorders." (PMID 36942499, 2023). "Previous studies have reported that SOCS3 is a target for treating metabolic disorders and influences insulin sensitivity and glucose homeostasis in the body." (PMID 37445769, 2023). "Inhibiting this process in AT triggers oxidative stress and the deterioration of insulin sensitivity, which can eventually lead to metabolic disorders." (PMID 37116707, 2023). "Berberine is the main bioactive component of Coptis which improves sensitivity of insulin and ameliorates metabolic disorders." (PMID 37483428, 2023). "DM comprises a group of metabolic disorders characterized by elevated blood glucose levels due to issues with insulin secretion and/or insulin function." (PMID 38276263, 2023). "In Pde3b-deficient mice, energy homeostasis regulation is altered, and metabolic disorders occur (including systemic insulin resistance)." (PMID 36675205, 2023). "On the other hand, a high-glucose diet is reported to increase gut permeability, the translocation of bacterial products, and insulin resistance, indicating that the gut–liver axis is likely to contribute to altered glucose homeostasis in metabolic diseases." (PMID 37569315, 2023). "Insulin signal transduction and NF-κB pathway represents a significant pathological connection between these metabolic disorders." (PMID 37907845, 2023). "Skeletal muscle is a major metabolic organ, and the decline of skeletal muscle quality and quantity leads to a decrease of insulin sensitivity and metabolic disorders." (PMID 37424859, 2023). "Browning is linked to increases in metabolic activity and flexibility as well as improved systemic insulin sensitivity, thereby presenting a new therapeutic strategy in the treatment of metabolic disorders like diabetes and obesity." (PMID 36895792, 2023). "Third, higher levels of SUA can impair the cells of the pancreas, damage the function of pancreatic β cells, reduce insulin secretion, and result in metabolic disorders." (PMID 37483942, 2023). "As far as metabolic disorders are concerned, oxidative stress restricts the amount of insulin secretion from the pancreatic β cells and impairs the glucose absorption in muscle and fat cells." (PMID 37374226, 2023). "DM is a metabolic disorder characterized by high plasma glucose levels due to dysfunction of pancreatic beta (β) cells, resulting in impaired insulin secretion, or due to decreased responsiveness of target cells to insulin." (PMID 37108792, 2023). "In the present years, NAFLD has also been recognized as metabolic-associated fatty liver disease (MAFLD) due to the presence of various metabolic disorders in patients, including disturbances in lipid, glucose, and insulin metabolism." (PMID 38187139, 2023). "Accumulating evidence showed that methionine restriction has favorable effects on health since it leads to improvement of insulin signaling, elevated energy expenditure, and decreased oxidative damage and inflammation in the context of metabolic disorders." (PMID 36923214, 2023). "A recent systematic review did not identify consistent changes in clinically relevant endpoints (such as insulin sensitivity) achieved in the recipient after FMT for metabolic diseases." (PMID 36836454, 2023). "Diabetes mellitus is a heterogeneous metabolic disease characterised by the faulty metabolism of carbohydrates, fats and proteins as a result of defects in insulin secretion or resistance." (PMID 36826003, 2023). "AMPK activation can improve insulin sensitivity and glucose homeostasis, and AMPK inactivation is associated with various metabolic disorders, reflecting its importance as a therapeutic target." (PMID 37538307, 2023).
metabolic disorders (continued). "DM is a metabolic disease characterized by high blood sugar levels due to problems with insulin secretion, insulin action, or both, and disrupted metabolism of carbohydrates, fats, and proteins." (PMID 37644936, 2023). "This bacterium has been shown to improve glucose tolerance, reverse diet induced metabolic disorders, insulin sensitivity, and improve the colon mucosal barrier." (PMID 36678256, 2023). "According to this theory, there is a vicious circle of fat accumulation in hepatocytes, lipotoxicity, metabolic disorders, inflammation, insulin resistance, and aggravation of metabolic disorders." (PMID 37834367, 2023). "Insulin resistance (IR) is a metabolic disorder with impaired insulin signaling and reduced glucose uptake by the target tissues." (PMID 37569834, 2023). "A beneficial probiotic microbe called Limosilactobacillus_reuteri modulates the intestinal milieu by producing antimicrobial compounds, enhances insulin sensitivity and glucose balance, and alleviates metabolic disorders." (PMID 38140087, 2023). "Loss of Akkermansia_muciniphila correlated with inflammation, impairment of insulin secretion and glucose homeostasis, metabolic disease, cancer immunotherapy, and homeostatic immunity." (PMID 37032862, 2023). "Impaired insulin action in WAT results in unrestrained lipolysis which is a major cause of reduced lipid storage capacity in dysfunctional WAT and metabolic disease." (PMID 37100238, 2023). "It has also been proved that RS can decrease the postprandial blood glucose, increase the insulin sensitivity and improve the metabolic disorder of glucose and lipid in type 2 diabetic patients." (PMID 37476405, 2023). "Treatment with insulin therapy can lead to weight gain, which will generate the already-described metabolic disorders." (PMID 37371662, 2023). "In a recent study in which authors applied topical cooling on VAT in a swine model of metabolic disease, it was reported that the cooling of VAT induced 30% loss in mesenteric fat volume, improved insulin sensitivity and blood pressure in this model." (PMID 37770553, 2023). "Next, metabolic disorders of adipocytokines will trigger a cascade of signals to reduce insulin sensitivity in peripheral tissues." (PMID 37830511, 2023). "T2DM is a collective term encompassing a range of endocrine and metabolic disorders primarily characterized by abnormal glucose metabolism due to a relative insufficiency of insulin." (PMID 37957155, 2023). "Microbial populations can impact host metabolism, intestinal development, and insulin secretion and contribute to metabolic disorders." (PMID 37510368, 2023). "Serum levels of these cytokines are significantly increased in obese and insulin resistant individuals and drive metabolic diseases." (PMID 38024380, 2023). "When IR occurs, the body compensates by secreting excessive insulin, which leads to endocrine and metabolic disorders and exacerbates disease progression." (PMID 38102584, 2023). "The dysregulation of FOX-family factor activity by insulin, mediated through the 3-phosphoinositide pathway and GSK3β, leads to neurodegenerative diseases and metabolic disorders." (PMID 36834685, 2023). "It is a type of metabolic disorder in which a person has a high blood glucose level over some time due to insufficiency in insulin secretion or insufficiency in insulin activity of the body." (PMID 37374193, 2023). "Recent research has revealed the epigenetic role of insulin signaling via Snail and Slug in metabolic disorders." (PMID 36942499, 2023). "Enhancing hepatic NFIL3 activity in insulin-resistant conditions is advantageous for reducing glycaemic symptoms in metabolic disorders." (PMID 37559129, 2023). "T2DM is a metabolic disorder characterized by high blood glucose levels due to insufficient insulin secretion or improper insulin use." (PMID 38179344, 2023).
metabolic disorders (continued). "Understanding these dynamics offers vital insights into the development of more effective strategies for managing insulin resistance and preserving pancreatic β-cell function, thereby advancing the treatment of metabolic diseases." (PMID 38203517, 2023). "T2DM is a metabolic disease characterized by chronic hyperglycemia with impaired insulin secretion and/or utilization." (PMID 37689643, 2023). "Such a metabolic-immune vicious cycle alters systemic glucose and lipid metabolism and insulin action, leading to metabolic diseases, including insulin resistance and type 2 diabetes." (PMID 36781473, 2023). "This disease has been described as a metabolic disorder with multiple etiologies, characterized by alterations in carbohydrate, fat, and protein metabolism due to insulin production anomalies." (PMID 36979696, 2023). "MET is the most prescribed T2D drug that is used to improve the insulin signaling and glycemic control which is commonly dysregulated in metabolic disease." (PMID 38010200, 2023). "Recent studies have found that GDF-15 regulates lipid and carbohydrate metabolism, reduces food intake and body mass, and improves insulin sensitivity, suggesting its potential therapeutic applications in metabolic diseases." (PMID 37152921, 2023). "In women with PCOS, metabolic disorders and increased oxidative stress lead to the abnormal functioning of the theca and granulosa cells of the ovary through the excessive insulin signaling of the IGF-1 receptors in the ovary." (PMID 37371662, 2023). "DM is a complex metabolic disorder characterized by high blood glucose levels due to insulin dysfunction, leading to various complications." (PMID 37513920, 2023). "It is a heterogeneous metabolic disorder characterised by the faulty metabolism of carbohydrates, fats and proteins as a result of defects in insulin secretion or resistance." (PMID 36826003, 2023). "Though these drugs can enhance insulin sensitivity, promote insulin secretion, and improve metabolic disorders, there are still a large number of patients suffering from poor blood glucose control, serious complications and drug side effects." (PMID 38273819, 2023). "DM is a group of metabolic diseases characterized by chronic hyperglycemia due to defects in insulin secretion, insulin action, or both." (PMID 35213996, 2022). "SAT and VAT are functionally heterogeneous and contribute differently to metabolic diseases depending on their differential capacities of lipolysis, lipogenesis, insulin sensitivity, and secretion of inflammatory cytokines." (PMID 35646489, 2022). "The number of islet β-cells changes with the severity of glucose metabolism disorders and insulin secretion." (PMID 35740008, 2022). "In summary, using SelSH-KO mice, we first found hepatic SelS deficiency increases ER stress, resulting in hepatic lipid accumulation and impaired insulin signaling, while SelS overexpression protects primary hepatocytes from these metabolic disorders." (PMID 35347118, 2022). "Metformin, GLP-1RA, and TZDs are widely used antidiabetic drugs that increase insulin sensitivity and improve metabolic disorders." (PMID 36568071, 2022). "IR is a metabolic disorder in which an individual’s sensitivity to exogenous or endogenous insulin is reduced, resulting in the body’s inability to use insulin to adjust blood glucose levels, leaving blood glucose at a consistently high level." (PMID 36589825, 2022). "This high morbidity and the unique physiologic features of insulin sensitivity and secretion in youth drive the necessity to specifically investigate the systems involved in metabolic disease development in youth." (PMID 35991189, 2022). "This review discusses the mechanism of O-GlcNAcylation to alleviate metabolic disorders and the controversy about the insulin resistance of skeletal muscle." (PMID 35681484, 2022).
metabolic disorders (continued). "This is the first study aiming to test the reliability of the SPISE index as an indicator of insulin sensitivity in children and to assess its predictive value for the identification of glucose-insulin metabolism disorders later in life." (PMID 34142364, 2022). "Numerous recent studies have reported the role of R4 subfamily members in metabolic disorders, insulin secretion, and resistance." (PMID 36497154, 2022). "Type 2 Diabetes (T2D) is a common metabolic disorder resulting from a combination of inadequate secretion of insulin from β-cells and resistance to insulin action in insulin-dependent tissues such as adipose, liver and muscle tissues." (PMID 36364703, 2022). "Vaspin, a member of serine protease inhibitor family is an insulin-sensitizing adipokine which upregulated in metabolic disorders to compensate insulin signaling and also in inflammation." (PMID 35630058, 2022). "The effects of natural compounds on metabolic disorders differ, and include amelioration in energy expenditure, insulin secretion, glucose utilization, satiety, or beneficial interference with the gut microbiome." (PMID 36500538, 2022). "Many recent studies have demonstrated that AD is a degenerative metabolic disease characterized by a defective glucose utilization, brain insulin responsiveness, and energy metabolism, which are risks factors to oxidative stress and neuroinflammation." (PMID 35204710, 2022). "In a longitudinal study, biomarkers associated with metabolic disorders such as the HOMA index and insulin sensitivity were associated with the fatty acid profile." (PMID 36615745, 2022). "DM is a group of metabolic diseases characterized by chronic hyperglycemia resulting from defects in insulin secretion, insulin action, or both." (PMID 36045662, 2022). "In the process of a project to find modulators of the human insulin promoter, with the goal of developing therapeutics for metabolic disease, we developed a novel cell-based assay in which GFP is expressed under the control of the human insulin promoter." (PMID 35385524, 2022). "Disruption of insulin action in the brain leads to alterations in not only metabolic disorders but also neurodegenerative diseases." (PMID 35173604, 2022). "DM is a group of metabolic diseases marked by high levels of blood glucose resulting from problems in insulin production, insulin use, or both." (PMID 36910351, 2022). "Regular exercise has long been considered to be an effective non-pharmacological approach to strengthen anti-oxidant defenses and improve mitochondrial function, insulin sensitivity, and metabolic control in several tissues and metabolic disorders." (PMID 36531176, 2022). "The prevalence of metabolic diseases is increasing, leading to more women entering pregnancy with alterations in the glucose-insulin axis." (PMID 36497026, 2022). "This is in line with the known role of DPP4 in metabolic diseases as major incretin hormones responsible for postprandial insulin secretion are among the substrates of its peptidase activity." (PMID 36168895, 2022). "Type 1 DM is a metabolic disease in which individuals lose the ability to produce insulin, due to autoimmune destruction of insulin-producing β cells." (PMID 36125898, 2022). "Following the low concentration of circulation insulin, the progress of metabolic diseases such as MetS can prevent." (PMID 36585722, 2022). "Elafibranor, a dual PPARα/δ agonist treatment for NASH patients, was demonstrated to improve insulin sensitivity, metabolic disorders, and inflammation." (PMID 35887189, 2022). "Early evidence suggests that adipose tissue-derived exosomes contribute to the development of metabolic disorders such as obesity and insulin resistance by regulating distant organ tissues, such as the liver and pancreas." (PMID 35600580, 2022).